MSN (moesin)
Diseases named in the same sentence as MSN in open-access papers (continued):
Sharing a sentence is not in itself a finding about the gene and the disease.
cervical carcinoma (6 papers, 2010 to 2021). A carcinoma arising from either the exocervical squamous epithelium or the endocervical glandular epithelium. "In the present study, we purpose to investigate the effects of VEGF-C on actin cytoskeleton remodeling and on cervical cancer cell migration and to characterize the role of moesin and the signaling cascade implicated in these actions." (PMID 20429915, 2010). "Indeed, moesin gene expression is shown to be strongly associated with metastatic phenotypes of cervical cancer." (PMID 20429915, 2010). "The relative mRNA expression levels of ezrin, radixn, and moesin in HeLa cells were higher and that of PD-L1 was moderate among a variety of human cervical cancer cell lines." (PMID 34577118, 2021). "We detected previously unreported recurrent mutations in cervical cancer in GPX1, MSN, FAS, KRT8, and SPRED3, all genes known to modulate tumorigenic processes." (PMID 34620846, 2021). "Eventually, Y-27632 inhibited ROCK-2 and therefore impaired VEGF-C-induced moesin expression and phosphorylation in cervical carcinoma (SiHa) cell line." (PMID 32443784, 2020). "VEGF‐C accelerated cervical cancer invasiveness via regulation of galectin‐3 or moesin protein expression (Liu, Cheng, He, & Yao, 2014)." (PMID 31478352, 2019). "ROCK2, an important signaling molecule, can promote cervical cancer metastasis by upregulating and activating the expression and function of moesin protein through RhoA/ROCK2 pathway." (PMID 24992025, 2014). "Taken together, we demonstrated that VEGF-C activated RhoA/ROCK-2/moesin cascade in cervical cancer cells, leading to the accelerated cancer cell migration and invasion." (PMID 20429915, 2010). "In this study, we investigated the effects of VEGF-C on actin cytoskeleton remodeling and on cervical cancer cell migration and invasion and how the actin-regulatory protein, moesin regulated these effects through RhoA/ROCK-2 signaling pathway." (PMID 20429915, 2010). "Therefore, moesin expression may serve as a potential marker for cervical cancer metastasis, which need be further clinically investigated." (PMID 20429915, 2010). "In another human cervical cancer cell line, OMC4, all three ERM were detected at protein levels, but the relative expression levels of radixin and moesin were lower than that of ezrin." (PMID 34577118, 2021). "Cervical cancer metastasis is promoted by VEGF-C upregulating and activating moesin protein through RhoA/ROCK-2 pathway." (PMID 32443784, 2020). "The increased sample size enabled identification of SMGs previously unreported in cervical carcinoma including NBPF10 (8%), RANBP2 (6%), MSN (6%), KRT8 (6%), POTEC (6%), ZC3H11A (4%), BMS1 (4%), GPX1 (3%), OTOP1 (3%), DNAH12 (2%), COIL (2%), TBC1D26 (2%), SPRED3 (2%), FAM115A (2%), and ARIH1 (1%)." (PMID 34620846, 2021).
colorectal cancer (6 papers, 2022 to 2024). A primary or metastatic malignant neoplasm that affects the colon or rectum. "Similarly, higher moesin expression has been associated with poor prognosis in patients with colorectal cancer." (PMID 39457653, 2024). "Our findings suggest that MSN facilitates the progression of colorectal cancer by activating the β-catenin–RUNX2 axis, highlighting the potential of MSN as a promising therapeutic target for treating CRC." (PMID 37446127, 2023). "MSN promotes colorectal cancer progression through the β-catenin-RUNX2 signaling axis." (PMID 38430423, 2024). "Studies suggest that MSN could be a novel therapeutic target for colorectal cancer." (PMID 39445005, 2024). "RUNX2 is upregulated in gastric cancer, and in colorectal cancer patients, the expression levels of RUNX2 and MSN are significantly correlated, with both being overexpressed." (PMID 38430423, 2024). "Overexpression of moesin promotes cancer cells to proliferate and migrate via the β-catenin-RUNX2 interaction, suggesting that moesin may function as a potential therapeutic target for colorectal cancer." (PMID 39457653, 2024). "Thus, together, the findings of our study emphasize the targeting of MSN in CRC treatment and suggest that the development of therapeutics for colorectal cancer patients with high MSN expression could enhance treatment efficacy." (PMID 37446127, 2023). "A similar targeting profile was observed for hsa-miR-192-5p: the canonical form bound EMT master-regulator ZEB2 and angiogenesis stimulator WNK1, while non-canonical 5′-isomiR regulated two other colorectal cancer oncogenes: NOX4 and MSN." (PMID 36275459, 2022).
lymphopenia (6 papers, 2013 to 2024). Reduction in the number of lymphocytes. "We observed that the moesin deficiency delayed FTY720-induced lymphopenia in vivo." (PMID 24358210, 2013). "We report a patient with adult-onset neutropenia, lymphopenia, inadequate response to the pneumococcal polysaccharide vaccine (PPSV23), and recurrent bacterial infections associated with a hemizygous MSN deletion." (PMID 39781543, 2024). "Highly expressed in lymphocytes, moesin determines the formation of the immunological synapse in B and T cells and controls the proliferation of CD8+ and CD4+ Tregs, whose deficiency has been found to result in persistent lymphopenia in the peripheral blood." (PMID 37711606, 2023). "Furthermore, treating moesin-deficient mice with FTY720, an S1P receptor agonist known to internalize S1PR1, caused delayed lymphopenia, and lymphocytes isolated from FTY720-treated moesin-deficient mice still responded to S1P ex vivo in chemotaxis assays." (PMID 24358210, 2013). "As such, a lack of moesin protein could prevent efficient lymphocyte migration and egress from lymphoid organs causing persistent absolute lymphopenia in the peripheral blood, as observed in the case." (PMID 29556235, 2018). "Moreover, we showed that FTY720-induced lymphopenia is delayed in moesin-deficient mice, and that T cells from FTY720-treated moesin-deficient mice respond to S1P in chemotaxis assays, indicating that the loss of moesin causes an S1PR1 internalization defect in vivo." (PMID 24358210, 2013).
oral squamous cell carcinoma (6 papers, 2010 to 2022). "MSN expression correlates with poor prognosis in oral squamous cell carcinoma and basal breast cancer, a subtype with high risk of metastasis and recurrence." (PMID 21501518, 2011). "Immunohistochemical expression of moesin in the invasive front of oral squamous cell carcinomas was weak in 40 tumors, while in 44 tumors the expression was strong." (PMID 29310601, 2018). "For oral squamous cell carcinomas in patients with weak moesin expression the survival rate varied from 22.7% in 5 years to 6.8% in 10 years." (PMID 29310601, 2018). "This study aimed to evaluate the participation of moesin and podoplanin in the invasive tumor front of oral squamous cell carcinomas, and their influence on patients’ prognosis." (PMID 29310601, 2018). "The immunohistochemical expression of moesin in the invasive front of oral squamous cell carcinomas was predominantly strong, homogenously distributed on the membrane and in the cytoplasm of tumor cells." (PMID 29310601, 2018). "The overall survival rate, in 5 years and 10 years, for patients with oral squamous cell carcinomas and strong moesin expression was reduced from 38.5%, to 23.8%, respectively." (PMID 29310601, 2018). "Strong moesin expression was considered an unfavorable prognostic factor for patients with oral squamous cell carcinomas, clinical stage II and III (p = 0.024)." (PMID 29310601, 2018). "Recently, the overexpression of moesin in tumors has been correlated with metastasis and poor prognosis for the patient, including those with oral squamous cell carcinomas." (PMID 29310601, 2018). "Confirming these results, other authors described the membranous and cytoplasmic moesin expression in oral squamous cell carcinomas." (PMID 29310601, 2018). "The overall survival and the prognostic value of moesin and podoplanin expression in oral squamous cell carcinomas were analyzed in this study." (PMID 29310601, 2018). "The moesin immunoprofile in the invasive front of oral squamous cell carcinomas, clinical stages II and III, was predominantly cytoplasmic and strong." (PMID 29310601, 2018). "Actually, high expression of ERM proteins has been identified as the prognostic markers in clinical cancers and the expression pattern of moesin can be regarded as an independent prognostic factor in patients with oral squamous cell carcinoma." (PMID 20429915, 2010). "Overall analysis of podoplanin and moesin expression in oral squamous cell carcinomas was not statistically associated (p = 0.460)." (PMID 29310601, 2018). "Podoplanin and moesin immunoexpressions were evaluated by a semi-quantitative score method, based on the capture of 10 microscopic fields, at 400X magnification, in the invasive tumor front of oral squamous cell carcinomas." (PMID 29310601, 2018). "Moesin expression was considered a significant prognostic factor for oral squamous cell carcinomas." (PMID 29310601, 2018). "This study was in agreement with the present results, which indicated that the weak expression of moesin could be related to higher survival rates in oral squamous cell carcinoma patients." (PMID 29310601, 2018). "The weak immunohistochemical expression of moesin by neoplastic epithelial cells could be used as a favorable prognostic marker for oral squamous cell carcinomas." (PMID 29310601, 2018). "Moreover, malignant cells of oral squamous cell carcinomas expressed both podoplanin and moesin, but these proteins probably act individually in tumor invasion process." (PMID 29310601, 2018).
Alzheimer disease (5 papers, 2020 to 2025). A progressive, neurodegenerative disease characterized by loss of function and death of nerve cells in several areas of the brain leading to loss of cognitive function such as memory and language. "In neurodegenerative diseases, such as Alzheimer’s disease (AD), moesin has been associated with cognitive decline." (PMID 39457653, 2024). "Collectively, these data suggest that pathogenic tau drives the elevation of Moesin detected in human Alzheimer’s disease and that aberrant Moesin activation mediates actin over-stabilization, cell cycle activation, and consequent neuronal death in tauopathy." (PMID 36879821, 2023). "We first asked if Moesin is elevated at the protein level in postmortem brains of patients with early and late stages of Alzheimer’s disease compared to age-matched controls." (PMID 36879821, 2023). "We also find that Moesin is elevated at the protein level in postmortem human brain from patients with Alzheimer’s disease, further suggesting a high degree of conservation between tau transgenic Drosophila and human Alzheimer’s disease." (PMID 36879821, 2023). "Moesin is a cytoskeletal adaptor protein, involved in the modification of the actin cytoskeleton, with relevance to Alzheimer’s Disease." (PMID 38106655, 2023). "After validating that overall levels of Moesin protein are significantly elevated in postmortem brains of patients with Alzheimer’s disease, we turned to Drosophila for additional functional and mechanistic analyses of Moesin dysregulation in the adult brain." (PMID 36879821, 2023). "As predicted by WGCNA, we detect a significant elevation in Moesin protein levels in frontal cortex of postmortem human Alzheimer’s disease brains at Braak V/VI based on immunostaining." (PMID 36879821, 2023). "In line with our analyses in human Alzheimer’s disease and the known involvement of Moesin in the EMT, we find that expression of human transgenic tau causes a depletion of adhesion proteins associated with EMT as well as neuronal cellular adhesion proteins in the adult Drosophila brain." (PMID 36879821, 2023).
breast tumor (5 papers, 2008 to 2023). "Amongst the genes of the proposed miR-200c MΦ migration signature, PPM1F and MSN were already established as miR-200c targets, altering the motility of breast tumor cells." (PMID 35336722, 2022). "In a screening of primary breast tumors, one study found that MSN was expressed at a low level in 65% of patients and at a high level in 19% of patients." (PMID 36231127, 2022). "Similar to the ERM protein family (i.e., ezrin and moesin), RhoA, RhoB and Cdc42 immunoreactivity was also observed in the stromal compartment of the breast tumour samples and its blood vessels." (PMID 23420497, 2013). "This fits with a previous report of a prominent expression of moesin in ER- human breast tumors, related to the tendency to metastasize." (PMID 18493596, 2008). "This is a similar observation to that of a recent study where activated Moesin competes with E3 ligase SPOP to prevent PD-L1 degradation and thereby promotes breast tumor progression." (PMID 37736741, 2023).
endometrial cancer (5 papers, 2008 to 2020). Primary or metastatic malignant neoplasm involving the endometrium (mucous membrane that lines the endometrial cavity). "E2 regulates the reorganization of actin filaments through phosphorylation of actin-binding proteins such as cofilin and moesin in neurons, fibroblasts, and breast and endometrial cancer cells." (PMID 32825553, 2020). "Since there is substantial evidence in the literature for FN1 and MSN being involved in cancer cell migration, we assayed the breast and endometrial cancer cell lines for expression of these proteins." (PMID 21501518, 2011). "The high level of MSN mRNA in our series of USC samples suggests that it could have potential value as an indicator for aggressive endometrial cancer phenotype." (PMID 21448288, 2011). "The purpose of this study is to determine the protein expression of MSN and CLDN7 in endometrial cancer (EC) and to evaluate their prognostic value." (PMID 22272721, 2012). "Using immunohistochemical stains, our work is the first to comprehensively study the protein expression of MSN and CLDN7 in correlation with the clinical characteristics in a large series of patients with endometrial cancer." (PMID 22272721, 2012). "The first objective of our study was to explore the MSN and CLDN7 protein expression in a large series of human endometrial cancers." (PMID 22272721, 2012). "In other TNBC cells and type 2 endometrial cancer cells, either MSN or FN1 are expressed but not both." (PMID 21501518, 2011).
lung adenocarcinoma (5 papers, 2019 to 2023). A carcinoma that arises from the lung and is characterized by the presence of malignant glandular epithelial cells. "Significant higher expression of MSN in lung adenocarcinoma and lung squamous cell carcinoma was observed through GEPIA and TCGA data base analysis." (PMID 37497401, 2023). "Significant higher expression of MSN in lung adenocarcinoma (LUAD) and lung squamous cell carcinoma (LUSC) was observed." (PMID 37497401, 2023). "And moesin has certain research results in many cancers in other aspects, but there are few about moesin in lung adenocarcinoma (LUAD)." (PMID 33838692, 2021). "RDX and moesin are downregulated in some lung adenocarcinomas, suggesting that these two molecules function as tumor suppressors in the early oncogenic stages." (PMID 33065998, 2020). "TMED2, MOESIN, DPYSL2, and LncRNA MEG3 have been discovered to enhance the occurrence and development of patients with lung adenocarcinoma via several immune-related regulatory mechanisms." (PMID 35354488, 2022).
bladder cancer (4 papers, 2014 to 2025). "MSN as a potential biomarker for predicting advanced bladder cancer has been found to have higher expression associated with poor survival in cancer." (PMID 36430344, 2022). "Our previous study has supported the oncogenic functions of MSN in human bladder cancer." (PMID 40696387, 2025). "In this study, we prioritized moesin (MSN) as a protein biomarker for early detection of BUC invasion using a liquid-based cytologic test, which is the most widely used clinical screening method for monitoring bladder cancer progression." (PMID 32326232, 2020). "Our proteomic data demonstrated that moesin (MSN) upregulation is one of the major factors for BUC invasion, which can be more critical as the previous proteomic analysis of urine extracellular vesicles revealed moesin as one of the candidate biomarkers for bladder cancer diagnosis." (PMID 32326232, 2020).
colon adenocarcinoma (4 papers, 2021 to 2024). "Radixin, moesin, and ezrin were preferentially distributed on the plasma membrane in human colon adenocarcinoma cells, However, the mRNA levels of ezrin and moesin were observed to be higher than those of radixin." (PMID 39457653, 2024). "In contrast, there are few reports showing the gene and protein expressions of moesin in human colon adenocarcinoma cells." (PMID 34577564, 2021). "Moreover, the gene correlation analysis revealed a positive correlation of PD-L1 with ezrin and moesin but not radixin in the clinical human colon adenocarcinoma samples from the TGCA database." (PMID 34577564, 2021).
HIV-1 infection (4 papers, 2013 to 2025). The type species of lentivirus and the etiologic agent of acquired immunodeficiency syndrome (AIDS). "Thus, there is a clear kinetic and spatial association between moesin phosphorylation and F-actin-mediated viral receptor capping that promotes HIV-1 infection." (PMID 23575248, 2013). "Based on the promotion and impairment HIV-1 fusion and entry by moesin and cofilin or syntenin-1, respectively, cortical actin has been proposed to be dynamically and temporally remodelled by the virus itself during early HIV-1 infection." (PMID 23575248, 2013). "Moesin functions as a negative regulator of R5-tropic HIV-1 infection after the membrane fusion step, but, in T cells, HIV-1 infection increases its RNA expression." (PMID 41226631, 2025). "Previous reports have established that phosphorylation of moesin, another member of the ERM family, is important for HIV-1 infection." (PMID 30210460, 2018). "Among these, focal adhesion proteins are required during early stages of HIV-1 infection, while the ezrin-radixin-moesin (ERM) family members, moesin and ezrin function as negative regulators of early post-entry infection, before or at the initiation of reverse transcription." (PMID 34229718, 2021).
invasive ductal carcinoma (4 papers, 2008 to 2020). "The authors also found that moesin was highly expressed in 95% of the cases in metaplastic carcinoma and 16% in invasive ductal carcinoma suggesting a role for moesin in EMT." (PMID 33171868, 2020). "Accordingly, the expression of p-Moesin in metastase tissues was also higher than that in primary foci of invasive ductal breast carcinoma." (PMID 33292278, 2020). "Different from normal breast tissues or fibroadenomas, invasive ductal carcinomas showed a deranged moesin and P-moesin cellular localization, with four main expression/distribution patterns." (PMID 18493596, 2008). "In addition, human samples of normal breast tissue, fibroadenomas and invasive ductal carcinomas show that the expression of wild-type moesin as well as of its active form is deranged in cancers, with increased protein amounts and a loss of association with the cell membrane." (PMID 18493596, 2008). "We analyzed the p-Moesin expression levels in 55 samples, including 34 BrCas (8 ductal breast carcinoma in situ and 26 invasive ductal breast carcinoma), 2 benign breast disease, 13 lymph nodes and 6 adjacent normal tissues by IHC staining assays." (PMID 33292278, 2020).